IL1B (interleukin 1 beta)
Diseases named in the same sentence as IL1B in open-access papers (continued):
Sharing a sentence is not in itself a finding about the gene and the disease.
infection (continued). "Cytokines known as inappetence-inducing factors including IL-6, IL-1β, TNF, and IFN-g were not significantly different in the brain after infection, whereas IL-1α was significantly reduced (P < 0.0001) in the brain of both αCD8α treated and aIL-1a treated mice compared to RSV treated." (PMID 38382577, 2024). "Moreover, siRNA-mediated knockdown of NLRP3, not NLRP1b, reduced IL-1β release and cell viability in N2aC24L1-3 cells after IAV/WSN infection." (PMID 39194237, 2024). "This study utilized human cervical tissue explants as an infection model to demonstrate that GC inoculation increases the secretion levels of both the proinflammatory cytokines IL-1β and TNF-α and the antiinflammatory cytokines IL-10 but not TGF-β and IL-17A during the first 24 hours of infection." (PMID 39585777, 2024). "The results of this study showed that Tn::icmE and Tn::dotA mutant infections in THP1 macrophages did not affect the levels of inflammasome components, including caspase 1, IL-1β, and gasdermin D. This suggests that these mutants are unable to activate the inflammasome pathway." (PMID 38787259, 2024). "Aa mono-infection, but not the dual infection with Aa and Sg, resulted in the expression of virulence factors such as the cytolethal distending toxin (CDT), which is known to activate the inflammasome leading to IL-1β release." (PMID 39125663, 2024). "Interestingly, our results show that HMPV pre-infection did not impair the LPS-stimulated activation of NF-κB and HIF-1α, transcription factors that stimulate IL-1β mRNA synthesis in human cells." (PMID 37435074, 2023). "We found that after infection, cells from patients with AUD had a significant decrease in transepithelial resistance (TER) and showed enhanced secretion of several proinflammatory cytokines including TNFα, IL-1β, and IFNγ as compared with non-AUD cells." (PMID 37786945, 2023). "Furthermore, although not statistically significant, we observed higher levels of IL-1β (~ 3-fold) and IFN-γ (~2-fold) at the terminal stage of infection (day 7), relative to pre-infection levels." (PMID 38035334, 2023). "The levels of proinflammatory cytokines (IP-10, IL-1β, IL-6, IL-8, TNF-α and GM-CSF) and anti-virus-related factors (IFN-α, IFN-λ1 and IFN-γ) were upregulated in the blood samples of the six patients as compared those of the control patients without infection." (PMID 37090924, 2023). "However, CATH-1 significantly increased the secretion of IL-1β and IL-6 while it did not change the secretion of TNF-α when CATH-1 was incubated with cells at post-infection." (PMID 37605242, 2023). "Treatment with the caspase 1-specific inhibitor Y-VAD decreased IL-1β secretion for both strains from 4629.3 pg/mL (without Y-VAD) to 1294.3 pg/mL (with Y-VAD) during the infection with the NADL cp strain and from 252.9 pg/mL (without Y-VAD) to 63.5 pg/mL (with Y-VAD) with the NY-1 ncp strain." (PMID 37515181, 2023). "Therefore, we predict that F1 and A47 are largely non-functional during MVA infection because we observed inflammasome assembly, GSDMD processing, IL-1β secretion and pyroptotic cell death in MVA-infected macrophages." (PMID 38065956, 2023). "Functionally, loss of IL-1rn in vivo biases HSC differentiation into the myeloid lineage and induces excess myeloid lineage expansion reminiscent of early hematological disease, through IL-1r1 and IL-1β overactivation in HSC but not IL-1α, in the absence of injury or infection." (PMID 36596811, 2023). "However, comparisons between vaccinated mice showed that H7N7 infection did not significantly increase levels of CCL2 (p = 0.94), IFNγ (p = 0.97), IL1β (p = 0.52), and IL-6 (p = 0.59) in the lungs compared to vaccinated mice receiving PBS." (PMID 37063291, 2023). "Notable among these cytokines are TNFα, IL-1β, and IFNγ, where differences in IL-1β and IFNγ secretion between AUD and non-AUD cells were significant and there was a trending higher level of TNFα secretion by AUD cells at 6 and 24 h after infection." (PMID 37786945, 2023).
infection (continued). "In addition, no significant alteration in the levels of IFNγ, IL-1β, IL-4, IL-6, IL-8, IL-10, CXCL10, and TNFα was observed in peripheral blood after Vir-S74-T3Bo infection by comparing Att-S74-T3Bo-inoculated and naïve control animals." (PMID 36466866, 2022). "Furthermore, in a S. aureus craniotomy biofilm infection model, TLR2, but not TLR9, was critical for host bacterial containment through the caspase-1-mediated activation of IL-1β, which was reduced in the Tlr2−/− mice." (PMID 36226943, 2022). "Instead, infection with the virulent 22653/14 ASFV did not alter any surface marker expression and did not trigger the release of either IFNβ, anti-inflammatory IL-10, proinflammatory (IL-1β, IL-6, IL-8, TNF-α), and pro-Th1 (IL-12, IL-18) cytokines." (PMID 35215216, 2022). "Indeed, whereas IL-1b protein accumulation was not impacted by the absence of lymphocytes and was up-regulated by PAO1 infection (Figure 3C1), IL-23 and IL-22 were down-regulated by PAO1 treatment (Figure 3C2,C3)." (PMID 35955566, 2022). "However, the expression of NLRP3 and IL-1β genes after A. jandaei and A. piscicola infection of the THP-1 cells was very low and no different from the expression of the THP-1 cells without infection." (PMID 35874671, 2022). "Furthermore, knockdown of Nek7 significantly inhibited the secretion of IL-1β, but the secretion of IL-6, TNF-α, and IL-1α were not affected during PmCQ2 infection." (PMID 35350616, 2022). "We observed a similar increase in TUNEL+ cells in STM-infected HIOs treated with IL-1β without PMNs, compared to the infected PMN-HIOs, demonstrating that IL-1β signaling is sufficient to drive cell death in the absence of PMNs during STM infection." (PMID 36191054, 2022). "Given parturition being a process of inflammation of gestational tissues and the important role of LPS, IL-1β, and SAA1 in infection and noninfection-induced inflammatory reaction, our findings may be fitted into both normal and infection-induced parturition." (PMID 36206855, 2022). "Similarly to previously published work, the expression of the inflammatory cytokines (IL-1β, IL-6, IL-8, and TNF-α) after RVFV infection was upregulated to a greater extent in the absence of the RVFV NSs protein." (PMID 34835071, 2021). "In addition, WT cells exhibited similar amounts of IL-1α, IL-1β, and TNF-α release with and without treatment, but lower levels of CXCL1 and IL-6 in infection supernatants." (PMID 33441602, 2021). "Furthermore, greater expression of IL-1β, TNF, and IL-8 was still observed during infection with PAO1 than PA14 with or without the presence of CFTR(inh)-172." (PMID 33664232, 2021). "Real-time reverse transcription-PCR (RT-PCR) results showed that the expression of IL-1β mRNA was significantly induced in S. pneumoniae-infected macrophages of WT and NLRP6−/− mice at 9 h post infection, indicating that NLRP6 did not affect S. pneumoniae-induced IL-1β transcription." (PMID 33918100, 2021). "MTB bacterial burden in lungs and spleens, IL-1β and IL-1α concentrations in lung homogenates, the size, morphology and cellular composition of the lung lesions are not affected by NLRP3 absence following infection with virulent MTB via aerosol." (PMID 33503864, 2021). "Our results show that IL-4, IL-6, IL-8, IL-10, IL-12P70, IL-1β, IL-2, IFN-γ, TNF-α, TNF-β and IL-17A are in the lungs The expression level of bacterially infected individuals was higher than that of patients without any infections (P<0.05)." (PMID 34925324, 2021). "Likewise, infection of human monocytes with T. gondii activates NLRP3, which results in release of IL-1β, but without pyroptosis." (PMID 34670268, 2021). "Moreover, the microbiome composition was significantly different in samples collected during infection versus non-infection, and in samples with high versus low levels of the inflammatory biomarkers HBP and IL-1β." (PMID 33892717, 2021).
infection (continued). "Interestingly, IL-1β, IL-6, IL-10 and IL-12 were not significantly altered upon DAF depletion over the course of infection." (PMID 34197564, 2021). "Studies show elevated interleukin 1 beta during later stages of LASV infection in cynomologous macaques, but this and other markers of inflammasome activation have not been well characterized during human infection." (PMID 33079033, 2020). "Upon SMV strain infection, the HD11 cells produced IL-1β and IL-8 but not IFN and ISG transcripts." (PMID 32660114, 2020). "However, dietary BLJ supplementation remarkably downregulated TLR-4 and TRAF-6 gene expression levels, decreased IL-1β gene expression levels and increased A20 and SOCS-6 mRNA levels in the jejunal mucosa of broilers regardless of NE infection." (PMID 32110391, 2020). "The decreased production of IL-1β and IL-6 in phagocytes was likely not only due to active inhibition by DAT alone, as co-treatment with DAT-coated beads did not decrease production of these cytokines during WT infection when compared to control beads." (PMID 32695111, 2020). "Nevertheless, these unprimed WT macrophages displayed caspase-1 processing starting 12 hours after MNV infection, demonstrating that MNV itself has the capacity to trigger inflammasome activation even in the absence of sufficient amounts of pro-IL-1β that would contribute to inflammatory responses." (PMID 31017981, 2019). "Relatedly, we hypothesized that β-NAD+, which is not hydrolyzed during infection with nga(G330D) bacteria, might drive the P2X7-dependent increase in IL-1β release." (PMID 31275321, 2019). "L. amazonensis infection also increased the levels of TNF-α and IL-1β, and MPO activity in the ipsilateral, but not contralateral paw tissue of infected mice when compared to control non-infected animals at day 40 after the infection (p < 0.05)." (PMID 31138231, 2019). "However, when infected macrophages from Casp-11-/- mice were stimulated with ATP or LTB4, we did not observe IL-1β release, suggesting that IL-β induced by P2X7 receptor and LTB4 during infection are dependent on Casp-11." (PMID 31233552, 2019). "When PERP knockdown followed by treatment with MY1WT in dGCs, there is an opposite trend emerged of the mRNA expression level of TNF-α (P <0.05), however, overexpression of PERP or knockdown PERP showed no significant mRNA level change of IL-6, IL-1β, TNF-α, and IFN-γ during MY1ΔsipC infection." (PMID 31565575, 2019). "We observed robust IL-1β production in BMDMs from WT and Aim2–/–mice in response to infection with MAYV, but Nlrp3–/–, Asc–/–and Casp1/11–/–macrophages failed to induce IL-1β secretion." (PMID 31479495, 2019). "Similarly, at day 84 post-infection, no clear difference was observed in the concentration of IFN-γ, IL-1β, TNF-α, IL-12, IL-6, IL-10 and IL-4 in the both groups of mice." (PMID 31801478, 2019). "First, the fact that inflammatory mediators such as interleukin-1 beta (IL-1β), IL-6 and tumour necrosis factor (TNF) induce SAA suggests that SAA is a dedicated response enacted by the host during an infection or severe trauma and not a manifestation of pathology per se." (PMID 30268137, 2018). "However, upon infection, levels of released IFN-γ and IL-1β cytokines were diminished in ISG15−/− mice but not in control C57BL/6 mice or in UbE1L−/− mice, which are devoid of intracellular conjugation of ISG15 through ISG15 E1 enzyme deficiency." (PMID 29891555, 2018). "IL-1β drives the expression of IFN-β and ISGs in the absence of infection." (PMID 29559569, 2018). "Finally, we showed using a murine CBM model that F. pedrosoi elicits a NLRP3-regulated IL-1β and interleukin-18 release in vivo, but without NLRP3 inflammasome activation interfering in the course of the experimental infection." (PMID 29209318, 2017).
infection (continued). "The current study also identifies several factors, including IL-1α, MIP-1α, RANTES, IL-12(p40) and IL-12(p70) that are induced in aged mice but not young mice following infection (compared to PBS) and other factors, including IL-1β, IL-10, IL-13 and eotaxin that are specific to young mice." (PMID 27936166, 2016). "However, there were no HIF-1α-dependent differences in lung cytokine secretion, indicating that lung epithelial HIF-1α is not required to induce IL-1β, IL-6, CXCL1, CXCL2, or MIP-3α secretion during infection." (PMID 27624128, 2016). "Interestingly, ΔYopM infection in BMDMs failed to upregulate NLRP3 and HMGB1 secretion, but significantly induced caspase-1 activation and IL-1β secretion." (PMID 27929533, 2016). "After infection of not pre-treated THP-1 cells, an increase in IL-1β expression was observed." (PMID 27105429, 2016). "Also, liver caspase-1 contents were augmented to a comparable extent during infection in WT and SRBI−/− mice and levels of IL-1β were not significantly changed." (PMID 27694929, 2016). "Inhibition of MEK, P38 and JNK could impair the expression of TNF-α and IL-1β at the mRNA level, with the only exception that inhibition of JNK could not significantly decrease the mRNA of IL-1β during infection." (PMID 26317438, 2015). "However, monocyte-derived dendritic cells do not secrete proinflammatory cytokines of TNF-α, IL1β, IL6, IL10, or IL2, IFN-γ, or IL12 after infection with Ebola virus, though there are higher levels of certain chemokines (notably IL8 and MCP1)." (PMID 25592846, 2015). "In contrast, infection of primed NLRP3−/− cells with X31 showed no significant IL-1β production compared to the medium control, showing the NLP3-dependence of influenza virus-induced IL-1β production." (PMID 23737748, 2013). "Thus, even when murine infection is initiated with MHB-grown Ft the inflammatory response to actively replicating (now, host-adapted) bacteria at 24 h fails to include TNF, IL-1β, and IL-6." (PMID 23554897, 2013). "The administration of IL-1β dramatically increased the level of IL-17 production in the CNS of the resistant mice, which do not produce a high level of Th17 cells following TMEV infection." (PMID 22985464, 2012). "In contrast, macrophages infected with ΔatsR (herein T6SS+), lacking a negative regulator that results in the overexpression of the T6SS, showed higher levels of IL-1β secretion than those infected with the parental MH1K, while infection with ΔT4SS-2 does not affect IL-1β secretion (data not shown)." (PMID 22848580, 2012). "Stimulation of IL-6, IL-1β, and IL-17, independent of ClpV-mediated TNFα production, suggests that the T6SS may play a role in recruiting immune cells to the site of infection." (PMID 23071529, 2012). "Indeed, we found that in a mouse model of infection, WNV induced the acute production of IL-1β in vivo, and that animals lacking the IL-1 receptor or components involved in inflammasome signaling complex exhibited increased susceptibility to WNV pathogenesis." (PMID 23209411, 2012). "Strikingly, IL-6, IL-1β, IL-1α, IL-10, MIP-1α, and KC (data not shown) were secreted at significantly higher levels in response to infection with C. caviae compared to C. muridarum, whereas G-CSF (data not shown), GM-CSF (data not shown), and TNF-α levels were similar between the strains." (PMID 22292031, 2012). "Also, the local concentration of the pro-inflammatory cytokines TNFα and IL-1β and the chemokines KC and MIP-2 was not different between wild-type and Cd55-/- mice at 24 h and 48 h after infection (data not shown)." (PMID 21984892, 2011). "Mice treated with IL-1β depleting antibodies were not significantly more sensitive to CO92ΔyopH infection than the control mice and only 10% of the mice treated with the TNF-α depleting antibodies succumbed to infection." (PMID 20565713, 2010).
infection (continued). "In contrast, Il-1β, and Il-10 mRNA levels were not significantly different across strains, though the levels of Il-6 mRNA was markedly increased in MDA5−/− mice following infection." (PMID 20107606, 2010). "LPS treatment of uninfected THP-1 cells also co-induced the secretion of IL-1β and TNF to comparable levels (data not shown), suggesting that infection with vMyxM013-KO virus was as comparably robust at inducing these two cytokines as the triggering of TLR4 activation with LPS." (PMID 19851467, 2009). "In the current study, the high CD38 expression in old murine BMMs after infection with oral pathogens was not directly correlated with the activation of NF-κB, PI3K, and MAPK protein kinases nor the amount of pro-inflammatory cytokine (IL-1β, IL-6, and TNF-α) released in old murine BMMs." (PMID 40649955, 2025). "However, and in contrast, transcription of il1β was only mildly (not significantly) induced by bacterial infection in our control group, while it was enhanced in the pituitary of fish fed TRP for both 7 and 15 days, 4 h post infection." (PMID 38548769, 2024). "In parallel, compared to infection with 1457ΔatlE without exogenous DNA-supplementation, IL1B was significantly reduced, while there was a significant induction of IL10 expression (mean fold change: 1.156 ± 0.85) expression levels reminiscent of findings in untreated S. epidermidis 1457 infection." (PMID 39567551, 2024). "Nevertheless, the same treatment did not affect the genes regulating the proinflammatory cytokines il-8 and il-1β, which suggests that the MEK pathway may play a specific role in the antiviral response but not the proinflammatory process during early infection." (PMID 37112880, 2023). "Cytokine signaling of IL-1β, IL-23, IL-17A, CCL7, CXCL10, TRAIL, CD40L, and BAFF provides protection against acute WNV infection in mice; IL-10 and IL-22 aid in WNV pathogenicity; IL-6 and IL-12 had no apparent effect during infection; and CCL2, TNF-α, and FasL roles remain elusive." (PMID 36992514, 2023). "Although the immune cells producing IL-1β are not restricted to macrophages, these are cells in the first line of infection facing pathogens; therefore, the study of the Vibrio cholerae cytotoxin (VCC) as a PAMP in the earliest phases of infection is a field of investigation." (PMID 37108435, 2023). "The reduced levels of early-response cytokines (IL-6, IL-1β, and TNF-α) following LDRT after infection on both day 1 and 3 were increased in the anti-TGF-β mAb-treated group, which was similar to the levels in virus-infected mice without LDRT (infection + mouse IgG group)." (PMID 37304302, 2023). "Infection of WT and GsdmD-/- neutrophils with PP34ExoUS142A showed that Glycine did not modify neutrophil histone citrullination and DNA decondensation upon PP34ExoUS142A infection, although it efficiently protected cells from LDH release without affecting IL-1β release." (PMID 35849616, 2022). "As the study has shown, GSDMD deficiency reduces the secretion of IL-1β and IL-18 in not all infections, so whether GSDMD can promote the protective inflammatory triggered by pro-inflammatory cytokines (such as IL-1β and IL-18) in vivo after SEZ infection remains to be further studied." (PMID 36311722, 2022). "The splenocytes’ release of TNF-α and IL-1β was increased by 69% and 224.8%, respectively (all, &p < 0.05) while IL-6 and IFN-γ release was not significantly changed when mice were prophylactically immunized with V2/4 vaccine before infection (vs. non-vaccinated/infected mice)." (PMID 34497271, 2021). "In our model, glycine and MM containing glycine dampened IL-1β and LDH release if nigericin was used as stimuli when interacting with the cells for an extended period before inflammasome activation, but not when inflammasome activation was promoted by Δcap67 infection." (PMID 33380899, 2020).